MITF (melanocyte inducing transcription factor)
Diseases named in the same sentence as MITF in open-access papers (continued):
Sharing a sentence is not in itself a finding about the gene and the disease.
melanoma (continued). "Depending on MITF expression levels, melanoma cells can switch between proliferative and invasive programs." (PMID 24039954, 2013). "In melanoma B16 cells, the present study demonstrated that the CSC-associated molecules Wnt/β-catenin, c-Kit, and MITF were up-regulated by the stimulation of α-MSH." (PMID 23762150, 2013). "Described as a “lineage addiction” oncogene, MITF is amplified in 10–20% of melanomas; however, MITF has also been attributed tumor-suppressive roles." (PMID 24039954, 2013). "MITF expression is heterogeneous in advanced melanomas but is highly expressed at the early phases of melanocyte transformation." (PMID 23349796, 2013). "The ability of MITF to act as a prosurvival factor in melanoma is thought to partially rely on the transcriptional regulation of target genes that include two inhibitors of apoptosis: BCL2 and ML-IAP." (PMID 23480510, 2013). "Genomic amplification of MITF is found in 10% of primary and 20% of metastatic melanomas and correlates with decreased 5-year overall patient survival, yet it does not translate into a strong increased expression at the protein level." (PMID 24416617, 2013). "The melanoma inhibitor of apoptosis (ML-IAP) is an MITF target gene that promotes melanoma survival." (PMID 23480510, 2013). "The complex interplay of MITF with its direct targets, together with MITF-dependent up-regulation of miR-211, which in turn targets several genes that partake in important cellular processes, is likely to determine melanoma cell fate." (PMID 24039954, 2013). "Histological studies of melanoma show frequent expression of Slug, E-cadherin, and MITF but also considerable heterogeneity of expression of these proteins among individual cells from the same specimen." (PMID 23755070, 2013). "In the first approach we used dual label immunofluorescence to compare the relative expression of PAX3 and MITF in adjacent regions within the same melanoma tissue section." (PMID 24062982, 2013). "Exogenous CDK2, osteopontin, or IGF1 each alone partly relieved the block of proliferation imposed by BRG1 depletion, implicating that more factors, besides the MITF target genes, are involved in melanoma cell survival." (PMID 23349796, 2013). "We present here several lines of experimental evidence supporting the notion that PAX3 and MITF expression indeed play independent roles in melanoma progression and cell migration." (PMID 24062982, 2013). "Lastly, we show that the morphological effects of knocking down PAX3 versus MITF in melanoma cells differ." (PMID 24062982, 2013). "ML-IAP has a restricted range of expression, being highly expressed in melanoma cells that express MITF and in some additional cancer cell lines." (PMID 23480510, 2013). "Among these genes, 15 are both up-regulated in melanoma cell lines with invasive phenotype and down-regulated in A375 melanoma cells over-expressing MITF." (PMID 24344100, 2013). "A recent study reported that degradation of MITF is related to the suppression of the α-MSH-induced cAMP-dependent melanogenic pathway in melanoma cells." (PMID 24129178, 2013). "By transcriptionally up-regulating TRPM1, MITF, which is critical for both melanocyte differentiation and survival and for melanoma progression, indirectly drives the expression of miR-211." (PMID 24039954, 2013).
melanoma (continued). "SWI/SNF enzymes interact with the microphthalmia-associated transcription factor (MITF), a lineage addiction oncogene, to promote MITF target gene expression in melanoma cells." (PMID 23480510, 2013). "We previously characterized a panel of melanoma cell lines for expression levels of MITF and PAX3, and cell migratory behaviors." (PMID 24062982, 2013). "The present study are aimed to further examine the role of α-melanocyte-stimulating hormone (α-MSH) signal transduction involving Wnt/β-catenin, c-Kit, and MITF, known pathways to produce melanin and have been considered as CSC-associated markers in melanoma." (PMID 23762150, 2013). "In the majority of melanoma cell lines and patient samples, MITF and miR-211 levels seem reduced compared to normal melanocytes or nevi." (PMID 24039954, 2013). "Firstly, we show that in melanoma tissues expression of MITF and PAX3 occur independently, and are variable from region to region, and furthermore that the expression of PAX3 is not correlated with Ki67 expression, a marker of cell proliferation." (PMID 24062982, 2013). "With this in mind, the emergence of MITF's role in melanoma and its high frequency of duplication, it seems contradictory that MC1R mutants predispose individuals to this disease." (PMID 22316093, 2012). "This is of particular interest, because MITF is commonly deregulated and is even designated a common oncogene in melanoma." (PMID 22927992, 2012). "Mechanistically, MITF plays an essential role in the homeostatic upregulation of c-Met expression by direct binding to the c-Met promoter in melanoma cells and primary melanocytes." (PMID 22848417, 2012). "The TGF-β pathway, which is often dysregulated in melanoma, down-regulates MITF, while the α-MSH pathway up-regulates MITF expression." (PMID 22316093, 2012). "This is consistent with data showing Brn2 expression up-regulation by Ras and MAPK signaling and BRN2 repression of MITF expression in some human melanoma cell lines." (PMID 23173060, 2012). "Generally, melanoma cells express high levels of MITF, but this condition differs greatly among melanoma cell lines and cells in tumor tissue." (PMID 21860617, 2012). "While MITF expression in melanoma is variable across specimens, studies have suggested that alterations to the repertoire of signals that determine MITF activity dictate the proliferative and invasive potential of melanoma cells." (PMID 22848417, 2012). "In man, a correlation between MITF expression in primary melanomas and survival has been described, with de-differentiated melanomas being associated with poor prognosis." (PMID 23173060, 2012). "In contrast, transcript levels were significantly higher for TYR and MITF (each p<0.0001) in blood from healthy control subjects vs. melanoma patients, again both in blood samples drawn at the time of surgery as well as those drawn one week following surgery." (PMID 22829910, 2012). "In contrast, healthy controls had uniformly higher levels of TYR and MITF than melanoma patients (p<0.0001)." (PMID 22829910, 2012). "The basic helix-loop-helix leucine zipper transcriptional factor MITF has been shown to play a pivotal role in the development and differentiation of melanocytes, and can act as an oncogene as well in melanomas." (PMID 22848417, 2012). "In conclusion with this findings, if MITF is reduced in melanoma cells, it will have less expression of TRPM1 and consequently of miR-211." (PMID 21860617, 2012). "RACK1 protein was detected with intense, diffuse and homogenous staining in MITF-positive cells of equine melanomas." (PMID 22747534, 2012).
melanoma (continued). "The genes most strongly upregulated by loss of either GCN5 or N-myc included transcription factors such as MITF, which is important in retinal development and melanoma." (PMID 22745758, 2012). "In fact, since MITF reduces melanoma cell proliferation and tumorigenicity, there is less MITF expressed in melanoma cells than in normal melanocytes." (PMID 21860617, 2012). "To explore this possibility, we performed expression profiling analysis with MITF knockdown melanoma cells." (PMID 22570637, 2012). "RAB17 expression is regulated by MITF in mammalian cell lines (melanomas) and melanocytes with RAB17 knockdown have reduced filopodia formation, leading to impaired melanosome transfer." (PMID 22937744, 2012). "Geoditin A at sublethal doses (≤5 μg/mL) decreased melanogenesis and glycosylation of tyrosinase (TYR) in murine B16 melanoma cells in a dose-dependent, but ROS- and MITF-independent manner." (PMID 22412813, 2012). "In the development of melanoma, however, an optimized level of MITF as an oncogene for proliferation and survival of tumor cells needs to be maintained by BRAF." (PMID 22007305, 2011). "Several transcription factors directly control MITF gene transcription to regulate melanocyte and melanoma development." (PMID 22046555, 2011). "It has been shown that LGALS3 is regulated by the microphthalmia-associated transcription factor (MITF), which has a pivotal role in melanocyte development and melanoma." (PMID 22216283, 2011). "MITF is expressed in most human melanomas, and stability of its expression is essential for melanoma cell proliferation and survival." (PMID 22046555, 2011). "Antiapoptotic activity and resistance to chemotherapy of melanoma are under the control of MITF activity." (PMID 22046555, 2011). "A genome-wide analysis of copy number alterations in cancer identified MITF as an amplified locus in melanoma." (PMID 21479172, 2011). "Analysis of the expression profile and function of MITF and identification of its target genes are important to better understand the complex system of melanoma development and progression." (PMID 22046555, 2011). "A low level of MITF expression promotes proliferation in melanoma, whereas a high level of MITF expression promotes differentiation through induction of cellular senescence and melanin production." (PMID 22046555, 2011). "Microphthalmia-associated transcription factor (MITF) is a master regulator gene of melanocyte development and differentiation and is also associated with melanoma development and progression." (PMID 22046555, 2011). "Extensive analyses of MITF will lead to a better understanding of melanoma development and progression and to the establishment of more effective therapeutics." (PMID 22046555, 2011). "BIRC7 transcription is also directly activated by MITF, and overexpression of BIRC7 rescued melanoma from apoptosis in MITF-depleted melanoma cells." (PMID 22046555, 2011). "Especially the lack of an inhibition by miR-137 and miR-182 was found to result in an overexpression of MITF, a master regulator in benign melanocytes as well as melanoma." (PMID 22007305, 2011). "MITF depletion in melanoma cells represses not only transcription of HIF1α but also that of vascular endothelial growth factor (VEGF), which is a target of HIF1α and has been demonstrated to be a major contributor to angiogenesis." (PMID 22046555, 2011). "Taken together, these data suggest that the inhibitory effect of muscle cells upon melanoma cells is density-dependent and targets MiTF expression." (PMID 20174581, 2010). "We previously reported that BRG1 interacts with MITF, the master regulator of melanocyte differentiation and lineage addiction oncogene in melanoma." (PMID 20969766, 2010). "Along these lines, the two melanoma lines (MeWo and 501 Mel) that exhibit positive regulation of MITF by ATF2 also exhibited positive regulation of SOX10 by ATF2." (PMID 21203491, 2010).
melanoma (continued). "Our finding showed that MITF-Mdel expression is melanocyte/melanoma specific and thus potentially a valuable candidate biomarker for melanoma." (PMID 20163701, 2010). "Detection of microphthalmia-associated transcription factor (MITF)-M and MITF-Mdel mRNA expression in normal human melanocytes (NHEM) and melanoma by reverse transcriptase polymerase chain reaction." (PMID 20163701, 2010). "Restoration of BRG1 in a melanoma cell line that lacks BRG1 expression enhanced the expression of MITF target genes and promoted increased resistance to cisplatin." (PMID 20969766, 2010). "Low expression of miR-148a, 148b and 152 in the melanoma cell lines is therefore consistent with the relatively high level of MITF expression in these cells." (PMID 20644734, 2010). "Significantly increased levels of MITF, however, reduce melanoma cell proliferation and tumorigenicity." (PMID 20644734, 2010). "In agreement, inhibition of SOX10 expression by corresponding siRNA attenuated the increase in MITF transcription seen in shATF2-expressing human melanocytes or melanoma cells." (PMID 21203491, 2010). "MiTF is a master regulator of melanocyte development and a key transcription factor in melanoma progression." (PMID 21209915, 2010). "Surprisingly, the six melanoma lines fell into two classes based on distinct patterns of regulation of MITF by ATF2." (PMID 21203491, 2010). "It was recently shown that MITF mRNAs with shorter 3′UTR sequences are more abundant in melanoma cell lines than transcripts with full-length 3′UTR sequences." (PMID 20644734, 2010). "While the cutoff line for MITF-Mdel was above MITF-Mdel levels of all normal PBMCs and all of the non-melanoma cell lines, but above the MITF-Mdel levels of 22 of 30 (73.3%) melanoma cell lines, and 18 of 21 (85.7%) frozen melanoma tissue samples." (PMID 20163701, 2010). "We next assessed the effect of ATF2 on SOX10 and MITF expression in 12 additional human melanoma cell lines." (PMID 21203491, 2010). "Recent studies indicate a role for MITF, a master regulator of melanocyte development and biogenesis, in melanoma progression." (PMID 21203491, 2010). "Compared to A375 melanoma cells expressing wild-type MiTF (MiTF-WT), cells expressing MiTF-S73A mutant showed less p21WAF1/CIP1 accumulation and a delayed p21WAF1/CIP1 recovery after UVC." (PMID 20701798, 2010). "The MiTF gene is amplified in about 20% of melanomas and is capable of transforming normal melanocytes in certain genetic environments, therefore it has been suggested that MiTF can function as an oncogene." (PMID 20701798, 2010). "Here we demonstrate that the transcription factor ATF2 negatively regulates MITF transcription in melanocytes and in about 50% of melanoma cell lines." (PMID 21203491, 2010). "As MITF is a lineage survival oncogene in melanoma whose expression needs to be maintained at a certain level, it is likely that these miRNAs play an important role in regulating MITF mRNA levels in this cell type." (PMID 20644734, 2010). "A high percentage of metastatic tumors and a subset of primary melanomas have been found to harbor amplification of the MITF gene." (PMID 22545195, 2010). "Melanocytes from mice lacking active ATF2 expressed increased levels of MITF, confirming that ATF2 negatively regulates MITF and implicating this newly discovered regulatory link in melanoma development." (PMID 21203491, 2010). "Both naevi and primary melanoma samples show similar numbers of MITF-positive cells that also express PAX3 (97.2% and 94.5%, respectively)." (PMID 20421967, 2010). "On melanoma tissue microarrays, a high nuclear ATF2 to MITF ratio in primary specimens was associated with metastatic disease and poor prognosis." (PMID 21203491, 2010). "Overall, our observations demonstrate that ATF2 plays an important role in fine-tuning those levels and support the rheostat model proposed for MITF's role in melanoma development and progression." (PMID 21203491, 2010).
melanoma (continued). "In all, in about 50% of the melanoma cell lines ATF2 elicits negative regulation of MITF, similar to what was seen in human and mouse melanocytes." (PMID 21203491, 2010). "The effects of the miRNAs were further confirmed by transfecting the microRNAs into MeWo melanoma cells and then measuring the endogenous MITF mRNA and protein levels." (PMID 20644734, 2010). "Tumor suppression assays reveal that the muscle-mediated tumor suppressor effects do not generate resistant clones but function through the down-regulation of the transcription factor MiTF, a master regulator of melanocyte development and a melanoma oncogene." (PMID 20174581, 2010). "The transcription factor MITF has been shown to play a central role in melanocyte biology and in melanoma progression." (PMID 21203491, 2010). "Next we expressed MiTF-WT and MiTF-S73A in MiTF-negative A375 melanoma cells, and examined their accumulation after UVC." (PMID 20701798, 2010). "In agreement, chromatin immunoprecipitation (ChIP) assays confirmed increased binding of SOX10 to the MITF promoter in melanoma cells expressing shATF2." (PMID 21203491, 2010). "The significance of these findings is underscored by our observation of human melanoma tumors, in which high ratio of nuclear ATF2 to MITF expression was associated with poor prognosis." (PMID 21203491, 2010). "Both the overexpression and oncogenic role of MITF in melanoma development and progression has been demonstrated." (PMID 24281076, 2010). "Our results show that miRNAs play an important role in regulating MITF mRNA in melanoma through conserved sites in the 3′UTR." (PMID 20644734, 2010). "Our findings establish the importance of transcriptionally active ATF2 in melanoma development through fine-tuning of MITF expression." (PMID 21203491, 2010). "In order to test if these miRNAs affect the level of endogenous MITF mRNA in melanoma cells, we used qRT-PCR to determine MITF mRNA expression after transfecting MeWo melanoma cells with the miRNAs miR-124, miR-137 and miR-148." (PMID 20644734, 2010). "Three of four melanocyte samples (75%), 29 of 31 melanoma cell lines (93.5%) and 21 of 21 frozen fresh melanoma tissue samples (100%) were positive for MITF-Mdel." (PMID 20163701, 2010). "Overall, our cohort of 18 melanoma lines revealed that about 50% of the melanomas retained negative regulation of MITF by ATF2, as seen in the melanocytes (primary and cell lines)." (PMID 21203491, 2010). "As in a previous report, we found high GPNMB expression in an MiTF-positive melanoma cell line, SK-MEL-28." (PMID 21209915, 2010). "Given the central role of MITF in melanocyte development, and the implication of MITF in melanoma progression, we investigated the consequences of differential MITF expression in more detail." (PMID 20041153, 2009). "The results are in agreement with the observations that the MITF promoter is responsive to Wnt signaling in melanocytes, that β-catenin binds and trans-activates MITF, and that β-catenin induced melanoma growth requires MITF." (PMID 19234609, 2009). "Two such genes are the melanoma-specific oncogene MITF, which is selectively amplified and overexpressed in 20% of melanomas, and NKX2-1, which lies in the minimal amplified region of a lung-cancer-specific 14q13.3 amplicon found in up to 20% of lung cancers." (PMID 19285540, 2009). "Among the many factors binding to E-box elements is the recognized melanoma oncogene, MITF, functionally characterized as the master switch for melanocyte development." (PMID 19881911, 2009). "In melanomas, MITF targets a number of genes with antagonistic behaviors, including genes such as CDK2 and Bcl-2, which promote cell cycle progression and survival, as well as p21CIP1 and p16INK4A, which halt the cell cycle." (PMID 19828018, 2009).